LEP (leptin)
Diseases named in the same sentence as LEP in open-access papers (continued):
Sharing a sentence is not in itself a finding about the gene and the disease.
hepatocellular carcinoma (56 papers, 2008 to 2026). A malignant tumor that arises from hepatocytes. "The clinical association of leptin and leptin receptor expression with cancer patient outcomes has been explored, and the positive association of leptin with hepatocellular carcinoma risk was recently reported." (PMID 33799880, 2021). "An increasing number of studies have focused on the association between leptin, adiponectin levels and the risk as well as the prognosis of hepatocellular carcinoma." (PMID 33256658, 2020). "The study shows that high leptin levels were associated with a higher risk of hepatocellular carcinoma." (PMID 33256658, 2020). "The leptin rs7799039 polymorphism was associated with increased risk of hepatocellular carcinoma (G vs A: OR = 1.28, 95% CI (1.10, 1.48), P = 0.002)." (PMID 33256658, 2020). "A meta-analysis was performed to assess the correlation between leptin, adiponectin levels and risk and prognosis of hepatocellular carcinoma (CRD42020195882)." (PMID 33256658, 2020). "Leptin induced STAT3 phosphorylation has also been shown to be inhibited by addition of adiponectin in hepatocellular cancer cells, which is associated with increased suppressor of cytokine signaling 3 (SOCS3) signaling, a negative regulator of STAT3." (PMID 29156726, 2017). "Moreover, a leptin-induced upregulation of this growth factor caused both hepatocellular carcinoma and cholangiocarcinoma via a dominant ERK (extracellular signal-regulated kinase) pathway in a zebrafish animal model." (PMID 33316927, 2020). "Moreover, It has been mentioned that the release of various proteins from visceral adipose tissues, including adipokines, resistin, leptin, visfatin, and tumor necrosis factor α, can impact liver function, potentially causing inflammation, cirrhosis, and hepatocellular cancer." (PMID 38179344, 2023). "In hepatocellular carcinoma (HCC) there are risk factors potentially linked to leptin (e.g., chronic hepatitis B, chronic hepatitis C, alcohol consumption, aflatoxins, and the nonalcoholic fatty liver disease)." (PMID 34202969, 2021). "Due to inconclusive studies on the influence of adipose tissue and its adipocytokines in association with the HCC, the present study aims to review the influence of serum leptin in patients with hepatocellular carcinoma." (PMID 28076486, 2016). "Coherently with our results, in literature, it is reported that Acrp30 is able to antagonize the oncogenic actions of leptin on hepatocellular carcinomas." (PMID 33587254, 2021). "Aside from the mentioned factors, the expression of both methionine adenosyltransferase 1α (MAT 1α) and MAT 1β is necessary for the mitogenic effect of leptin in hepatocellular cancer cells." (PMID 34588926, 2021). "The opposite function of leptin in cell proliferation was reported in rat hepatocellular carcinoma, which occurs via a p38-MAPK-dependent signaling pathway to attenuate serum-induced H4IIE cell proliferation." (PMID 33799880, 2021). "In another report of human hepatocellular carcinoma, leptin/leptin receptor expression was observed in both tumor and endothelial cells, in parallel to the degree of angiogenesis." (PMID 33799880, 2021). "Previous studies reported that Acrp30 and leptin exhibit antagonizing effects in hepatocellular carcinoma; thus, we have analyzed in our cell model system the effects of leptin treatment itself or in combination with Acrp30." (PMID 33587254, 2021). "Assessment of the possible role of adiponectin, leptin and visfatin in HCV associated hepatocellular carcinoma (HCC)." (PMID 32212784, 2020). "In human hepatocellular carcinoma, leptin/leptin receptor expressions were detected in both tumor and endothelial cells in parallel with the degree of angiogenesis." (PMID 29682217, 2018). "This occurred despite previous use of these antibodies to specifically detect leptin and leptin-receptor in the hepatocellular carcinoma, breast, biliary tract, appendix and stomach." (PMID 29615085, 2018).
hepatocellular carcinoma (continued). "The significance of hyperleptinemia in breast, colorectal, and hepatocellular cancer has been well documented, and some studies suggest the role of leptin in thyroid cancerogenesis." (PMID 30627158, 2018). "The results previously studied are still inconsistent and contradictory, and leptin can be effectively involved in the occurrence and development of hepatocellular carcinoma." (PMID 28076486, 2016). "Previous studies have shown that leptin stimulated the proliferation of hepatocellular carcinoma HepG2 cells in a time- and dose-dependent manner, and knockdown of leptin resulted in notable reduction in proliferation rate." (PMID 27185268, 2016). "Other studies indicated that concomitant activation of the JAK/STAT, PI3K/AKT and ERK signaling played crucial roles in leptin-mediated invasion and metastasis of hepatocellular carcinoma cells." (PMID 27185268, 2016). "This is similar to the effects of leptin on human bone marrow stromal cells and rat hepatocellular carcinoma, wherein p42/p44 MAPK or p38 MAPK play roles in modulating leptin signaling." (PMID 26593914, 2015). "Previous studies are consistent with the prognostic value of serum leptin for overall survival rates in patients with gastric adenocarcinoma, hepatocellular carcinoma and colorectal adenocarcinoma." (PMID 24932291, 2014). "Recent evidence indicates that leptin shows a prognostic value for the overall survival rate in patients with gastric adenocarcinoma, hepatocellular carcinoma and colorectal adenocarcinoma." (PMID 24932291, 2014). "We propose that leptin is a key regulator of the malignant properties of hepatocellular carcinoma cells through modulation of hTERT, a critical player of oncogenesis." (PMID 20723213, 2010). "Leptin promotes the proliferation and inhibits the apoptosis of hepatoma cells." (PMID 37266440, 2023). "Moreover, visceral adipose tissues secrete a variety of proteins such as adipokines, resistin, leptin, visfatin and tumour necrosis factor α which can influence the liver function and lead to inflammation, cirrhosis and hepatocellular cancer." (PMID 36039792, 2022). "Leptin expression is increased in both hepatoma tissues and cell lines." (PMID 33925827, 2021). "Recently, through in vitro studies, it has been demonstrated that the inhibition of the PI3K pathway after leptin-derived peptides (OB3) treatment plays a vital role by reducing the expression of leptin-induced proinflammatory genes in hepatocellular carcinoma cells." (PMID 33316927, 2020). "Since resveratrol (RSV) is a modulator of lipid homeostasis in the liver, we investigated whether treatment with different doses of RSV restores appropriate leptin action and fat accumulation in palmitate-induced steatotic human hepatoma (HepG2) cells." (PMID 31842467, 2019). "Interestingly, in this study hepatoma cells enhanced anti-HCC immunity through secretion of leptin resulting in down-regulation of Treg activity and subsequent promotion of CD8+ T-cell responses." (PMID 28758929, 2017). "The key words used were hepatocellular carcinoma, leptin, adipokine." (PMID 28076486, 2016). "Trata-se de revisão bibliográfica baseada na metodologia do Instituto Cochrane; a busca de dados foi realizada na base de dados Science Direct, Scielo, Medline, Lilacs e Pubmed, empregando as seguintes descritores: hepatocellular carcinoma, leptin, adipokine." (PMID 28076486, 2016). "Besides regulating food intake and energy expenditure, leptin regulates the expression of the iron regulatory hormone, hepcidin, as demonstrated in human hepatoma cells." (PMID 25569627, 2015). "We also found that leptin could affect hepatocellular carcinoma progression and invasion through its interaction with cytokines and matrix mettaloproteinases (MMPs) in the tumorigenic microenvironment." (PMID 20723213, 2010).
hepatocellular carcinoma (continued). "Additionally, adipokines, resistin, leptin, visfatin, and tumor necrosis factor α (TNF-α) are proteins secreted by visceral adipose tissues that can affect how the liver functions and cause inflammation, cirrhosis, and hepatocellular cancer." (PMID 37374119, 2023). "Furthermore, leptin stimulation increased hepcidin mRNA in cultured human HuH7 hepatoma cells." (PMID 34136516, 2021). "The relationship of leptin (LEP) and polymorphism of leptin receptor (LEPR) were studied in patients with hepatocellular carcinoma (HCC) and compared with those with liver cirrhosis to find out the extent of the risk of LEPR on patients with HCC." (PMID 33369452, 2020). "Moreover, serum leptin has been proposed as a tumor marker in hepatocellular carcinoma." (PMID 33316927, 2020). "For example, in hepatocellular carcinoma (HCC), circulating levels of adiponectin, leptin, visfatin and resistin were significantly higher in HCC patients when compared with the control group." (PMID 40902078, 2025). "Analogously, in a c12 HCC graft model in mice, leptin treatment was found to weaken the suppressive function of Tregs and enhance the cytotoxic activity of CD8+ T cells against hepatoma cells." (PMID 39061246, 2024). "In the mouse, leptin the “satiety” hormone and leptin receptor are essential for expression of ApoM, but excess concentrations of leptin inhibited ApoM mRNA expression in a dose-dependent manner in the human hepatoma cell line HepG2, suggesting that leptin may mediate ApoM expression." (PMID 35945490, 2022). "In palmitic acid (PA)-treated human hepatocellular carcinoma HepG2 cells, the downregulation of miR-375 expression significantly reduced IL-6, TNF-α, and leptin, and increased adiponectin levels." (PMID 36613525, 2022). "Following, we cover current knowledge about the implication of leptin in the development of the most prevalent metabolic liver diseases, from NALFD to hepatocellular carcinoma (HCC)." (PMID 33316927, 2020). "In vitro studies have mimicked such findings, considering APN exerts anti-malignancy effects in hepatocellular carcinoma (HCC) cell lines, HepG2 and Huh7, via leptin inhibition." (PMID 23691481, 2012). "Interestingly, the leptin-derived peptide (mimetic), OB3, was able to abolish leptin-induced cell proliferation by reducing phosphoinositide 3-kinase (PI3K) activation and the expression of proinflammatory genes in hepatocellular carcinoma cells." (PMID 33799880, 2021). "Nuclear and cytoplasmic staining of leptin in non-neoplastic hepatocytes (left side of each picture), and negative (c), weak (d) or strong (e) leptin staining in hepatocellular carcinoma cells (right side of each picture)." (PMID 29615085, 2018). "It has been reported that leptin expression is highly correlated with expression levels of human telomerase reverse transcriptase (hTERT) and could affect cancer progression and invasion in hepatocellular carcinoma (HCC)." (PMID 27185268, 2016). "Prior investigation showed that leptin promotes hepatocellular carcinoma growth, invasiveness, and migration through concomitant activation of the JAK/STAT, PI3K/AKT and ERK signaling, which implicates the JAK/STAT pathway as a critical mediator of leptin action." (PMID 27185268, 2016). "A parallel finding, indicated that leptin, an adipokine that plays an important role in the regulation of satiety, has the ability to activate hepcidin signaling through the JAK/STAT (Janus kinase/signal transduction and activators of transcription) pathway in human hepatoma cells (Huh7)." (PMID 25569627, 2015).
cognitive decline (54 papers, 2010 to 2025). "Some studies have reported that greater adiposity and leptin in older adults are linked to a lower risk of AD-related cognitive decline." (PMID 41516046, 2025). "Impaired leptin signaling in the brain is also linked to an increased accumulation of Aβ and tau hyperphosphorylation, both of which are associated with cognitive decline and AD pathology." (PMID 41515969, 2025). "Several studies report that low plasma leptin levels in older adults, or in patients with AD, are associated with cognitive decline, abnormal amyloid/tau profiles, and higher risk of disease progression." (PMID 41516046, 2025). "In Tg2576 mice, Aβ can directly impair leptin signaling in the hypothalamus, which exhibits early weight loss and reduced plasma leptin levels before amyloid deposition or cognitive decline." (PMID 41516046, 2025). "Association between peripheral leptin and adiponectin levels and cognitive decline in patients with neurocognitive disorders ≥65 years." (PMID 31969813, 2019). "The longitudinal studies also demonstrated that higher leptin levels were associated with decreased risk of cognitive decline." (PMID 26693203, 2015). "In longitudinal studies, higher leptin levels were associated with a lower risk of AD and cognitive decline." (PMID 26693203, 2015). "Higher leptin levels have been related to a lower incidence of dementia, which is clearly associated with a dramatic cognitive decline." (PMID 22927962, 2012). "Simple assays of leptin/adiponectin ratios, resistin levels, or composite adipokine panels might identify individuals at metabolic risk for cognitive decline." (PMID 41155642, 2025). "However, given that AD pathology accumulates in the brain decades before the onset of cognitive decline, the possibility that AD pathology is associated with leptin levels (ie, reverse causality) cannot be completely excluded." (PMID 38700863, 2024). "Decreased plasma leptin levels are correlated with an increased risk of cognitive decline and AD." (PMID 38892118, 2024). "Emerging evidence suggests that targeting leptin signaling could be a promising therapeutic strategy to mitigate the cognitive decline associated with hippocampal leptin resistance." (PMID 39594988, 2024). "However, chronic obesity-related low-grade inflammation causes leptin resistance, which, in turn, increases the risk of cognitive decline and AD." (PMID 39273520, 2024). "Thus, in some studies, low plasma leptin levels in old age have been found to be associated with an increased risk of cognitive decline and AD development." (PMID 35563589, 2022). "Given the previous in vitro findings that adiponectin and leptin have a role against Aβ metabolism, the association of adipokines with cognitive decline might be also dependent on the presence of Aβ pathology." (PMID 36329496, 2022). "Such estimates may help to justify, plan, evaluate, and compare the effectiveness of interventions aiming at preventing cognitive decline that would consider leptin as a modifiable risk factor." (PMID 30893833, 2019). "Similarly, high leptin levels in the elderly were associated with decreased cognitive decline, and serum leptin levels inversely correlated with dementia." (PMID 29587359, 2018). "Therefore, restoring leptin signaling in the brain could be a viable approach to prevent or even reverse hippocampal atrophy and cognitive decline in patients with leptin deficiency." (PMID 39594988, 2024). "In addition, previous observational studies also support the notion that leptin may be protective against dementia, since low plasma leptin levels in late-life are associated with worsening cognitive decline and increased dementia risk." (PMID 36097042, 2022).
cognitive decline (continued). "Although the mechanisms responsible for the neuroprotective action of adiponectin and leptin remain to be elucidated, both have been implicated in improving cognitive function in normal ageing, and in reducing the incidence of cerebrovascular diseases, cognitive decline and dementia." (PMID 34731089, 2021). "Hormonal imbalances, including leptin resistance, cortisol dysregulation, and estrogen depletion in females, further exacerbate cognitive decline." (PMID 40337166, 2025). "Chronic exposure to air pollution is believed to cause systemic inflammation and metabolic disruptions, such as leptin resistance, resulting in increased adiposity and promoting cognitive decline." (PMID 41515969, 2025). "In the Health ABC cohort study, participants in the high leptin group were 34% less likely to experience clinically significant cognitive decline over a 4‐year period." (PMID 39822062, 2025). "Despite significant advances in understanding the relationship between hippocampal leptin resistance and cognitive decline, several gaps in knowledge remain." (PMID 39594988, 2024). "Addressing leptin resistance and optimizing leptin delivery to the brain represent critical future directions in the effort to combat cognitive decline and hippocampal dysfunction." (PMID 39594988, 2024). "who suggested higher leptin concentration were correlated with a less expressed cognitive decline in the elderly in a prospective, longitudinal cohort study." (PMID 38686200, 2024). "This relationship underscores the potential for targeting leptin pathways as a therapeutic strategy to mitigate cognitive decline and address the metabolic aspects of neurodegenerative diseases." (PMID 39594988, 2024). "As leptin signaling is compromised in these conditions, the link between metabolic dysfunction and cognitive decline becomes increasingly apparent." (PMID 39594988, 2024). "Leptin is a hormone secreted by adipose tissue, which is suggested to have a protective effect against cognitive decline, contributing to neuronal survival." (PMID 37049637, 2023). "Mechanistically, reduced adipose expandability leads to hypertrophic adipocytes, triggering inflammation, insulin and leptin resistance, blood-brain barrier disruption, altered brain metabolism, neuronal inflammation, brain atrophy, and cognitive decline." (PMID 38026693, 2023). "We investigated the interactive effect of plasma adiponectin or leptin and Aβ pathology on progressive cognitive decline and cortical thinning in individuals with MCI." (PMID 36329496, 2022). "Research indicates that individual leptin levels increase with age, and although evidence shows leptin protects against cognitive decline, this only seems to hold true for those with a healthy BMI, likely due to leptin resistance." (PMID 36012526, 2022). "Second, adipose tissue secretes leptin, which contributes to prevention of cognitive decline in older adults." (PMID 31817127, 2019). "Individuals with higher levels of leptin had nearly 50% less cognitive decline compared with those with lower leptin levels." (PMID 31133846, 2019). "In the following sections, we review key aspects of brain leptin signaling that are relevant for its role in cognitive decline and AD." (PMID 30692905, 2018). "Compared to those with low leptin level, the elderly with high leptin level show less cognitive decline during aging." (PMID 26881095, 2016). "High leptin level in individuals with small waist circumference is related to less cognitive decline over 10 years." (PMID 26881095, 2016). "Using the Modified Mini Mental State Exam, there is shown to be a protective quality of cellular leptin combating cognitive decline." (PMID 25251414, 2014). "First, evidence from cellular, animal, and human studies has demonstrated that leptin, a hormone secreted by adipose tissue, has neuroprotective effects and may help slow cognitive decline." (PMID 40823251, 2025).